CCL15-CCL14 (CCL15-CCL14 readthrough (NMD candidate))
Gene: Protein-coding gene on chromosome 17 (35,983,656 to 36,001,621, reverse strand). Ensembl gene ENSG00000275688.
Genetic constraint (gnomAD): Missense variants: 124 observed, 136.46 expected, observed/expected ratio (o/e) 0.91, 90% interval 0.79 to 1.05. Synonymous variants: 50 observed, 50.31 expected, observed/expected ratio (o/e) 0.99, 90% interval 0.79 to 1.26.